IL18 (interleukin 18)
Diseases named in the same sentence as IL18 in open-access papers (continued):
Sharing a sentence is not in itself a finding about the gene and the disease.
macrophage activation syndrome (76 papers, 2011 to 2026). A complication of rheumatic disease that is caused by excessive activation and uncontrolled proliferation of T lymphocytes and well-differentiated macrophages. "Each of these NLRC4 mutations cause severe/recurrent macrophage activation syndrome (MAS)-like episodes characterized by elevated IL-18 serum levels." (PMID 38090573, 2023). "IL-18 has attracted increasing attention as a key mediator in autoinflammatory diseases associated with the development of macrophage activation syndrome (MAS) including systemic juvenile idiopathic arthritis and adult-onset Still’s disease." (PMID 36211331, 2022). "It is often associated with an early onset (<2 years of age), macrophage activation syndrome and high interleukin (IL)-18 circulating levels." (PMID 36553101, 2022). "IL-18 has been implicated in many autoinflammatory diseases, including macrophage activation syndrome, inflammatory bowel disease, sarcoidosis and others." (PMID 36207373, 2022). "One of the characteristics of NLRC4-dysregulated diseases is high serum IL-18, and IL-18 blockade is effective in treating macrophage activation syndrome caused by NLRC4 mutation." (PMID 33178225, 2020). "These symptoms are associated with excessive levels of IL-18 and IL-1β, and recurring fever flares, a phenotype that is reminiscent of macrophage activation syndrome (MAS)." (PMID 31520179, 2019). "An imbalance of IL-18 and IL-18BP results in elevated free IL-18 circulating levels and contributes to IL-18-mediated diseases associated with inflammasome hyperactivation or pyroptosis, such as autoinflammatory diseases and macrophage activation syndrome." (PMID 41087719, 2025). "Clinical trials are underway to investigate the treatment of adult-onset Still’s disease and NLRC4-related macrophage activation syndrome (inflammatory diseases associated with high plasma IL-18 levels) using IL-18BP (ClinicalTrials.gov Identifier: NCT 02398435, NCT 03113760)." (PMID 30717382, 2019). "IL-18 inhibition has demonstrated therapeutic benefits in preclinical models of various inflammatory diseases, and its role has been implicated in several human conditions, including myocardial pathology, metabolic syndrome, inflammatory bowel disease, and macrophage activation syndrome." (PMID 41087719, 2025). "These mutations lead to an over expression of IL-18 that results in organ damage due to Macrophage Activation Syndrome (MAS) or hemophagocytic lymphohistiocytosis (HLH)." (PMID 36875111, 2023). "Even in the case of a Macrophage Activation Syndrome (MAS), where IL-18 has a causal effect, the patient received combined IL-1β and IL-18 blockade for 11 months." (PMID 36668761, 2022). "Although the underlying mechanisms of biallelic NLRC4 deficiency remain elusive, IL-18 blockade was shown to be effective in treatment of NLRC4-mediated macrophage activation syndrome indicating that epithelial-derived IL-18 might be a critical pathomechanistic driver." (PMID 36524121, 2022). "Patients with systemic juvenile idiopathic arthritis and adult-onset Still’s disease exhibit chronic excess of serum IL-18, which is associated with a high incidence of macrophage activation syndrome (MAS), although the mechanisms of IL-18 regulation in such diseases remain largely unknown." (PMID 35958573, 2022). "In addition, IL-18 causes macrophage activation syndrome and exacerbates inflammation." (PMID 34573030, 2021). "Indeed, clinical trials to investigate treatment with IL-18BP for adult-onset Still’s Disease and NLRC4-associated macrophage activation syndrome, inflammatory diseases associated with high plasma IL-18 levels, are ongoing (ClinicalTrials.gov Identifier: NCT 02398435, NCT 03113760)." (PMID 30717382, 2019).
macrophage activation syndrome (continued). "Interestingly, in both sJIA and AOSD, increased serum levels of IL-18 have been observed to correlate with disease activity and with the risk of developing the potentially life-threatening macrophage activation syndrome (MAS), a complication notable for its haemophagocytic activity." (PMID 30406861, 2018). "In this scenario, IL-18BP expression is elevated by interferon-γ as part of the inflammatory response and limits the effects of IL-18 reducing the likelihood of macrophage activation syndrome a potentially fatal over-stimulation of the immune response." (PMID 41592067, 2026). "The dysregulation of IL‐18 and IL‐18BP is significantly associated with immune‐mediated diseases, especially those where IFNγ plays a pathological role, such as macrophage activation syndrome (MAS)." (PMID 41532007, 2026). "It is known that inactivating inflammatory responses is critical, and that IL-18BP is involved to some extent as reduced inactivation of IL-18 by IL-18BP is a key component of macrophage activation syndrome." (PMID 41592067, 2026). "Maximum ferritin levels were significantly higher in patients with IHF than with either hemoglobinopathy or transplant, and highly elevated total IL-18 levels were distinctive to patients with Stills Disease and/or Macrophage Activation Syndrome (MAS)." (PMID 38978562, 2024). "The pathogenesis of SJIA is complex, with an autoinflammatory presentation involving proinflammatory cytokines such as interleukin (IL)-1 and Il-6, a risk of life-threatening macrophage activation syndrome (MAS) in some patients also involving other cytokines, such as interferon gamma and IL-18." (PMID 35268449, 2022). "Previous studies provide evidence suggesting a significant correlation between excess serum IL-18 and macrophage activation syndrome (MAS)." (PMID 35958573, 2022). "A majority of patients with COVID-19 exhibit a predominant IL-1/IL-6 signature, but can evolve into an IL-18/IFNγ signature mimicking cytokine profiles observed in other inflammatory diseases such as macrophage activation syndrome (MAS)." (PMID 32699149, 2020). "High levels of IL-18 have been demonstrated in patients with macrophage activation syndrome (MAS), in addition to those with ASD, and it is also believed that IL-18 is implicated in dysregulated innate immunity." (PMID 32698838, 2020). "Both sJIA and macrophage activation syndrome are triggered by a cascade discharge of some cytokines such as interleukin 1β, IL-6 and IL-18." (PMID 32911717, 2020). "IL-18 is a key player in autoinflammatory syndromes, such as familial Mediterranean fever (FMF) caused by pyrin mutations and the Macrophage Activation Syndrome (MAS) caused by NLRC4 gain of function mutations that are characterized by systemically elevated IL-18 levels." (PMID 33101286, 2020). "Macrophage activation syndrome is another disease where the clinical and hematologic abnormalities correlate with elevated free IL-18 levels." (PMID 30717382, 2019). "Alternatively, when the CS is caused by macrophage activation syndrome (MAF), the serum levels of interleukin 18 are elevated, while CS due to HLH is often characterized by elevated levels of TNF-a, interferon γ (IFN-γ), interleukin 1 (IL-1), IL-4, IL-6, IL-8, IL-10, IL-18, CXCL9, and CXCL10." (PMID 39518964, 2024). "sJIA has many characteristics of an autoinflammatory pathology, associated with an increased synthesis of pro-inflammatory interleukins such as IL-1, IL-6, and IL-18, as well as S100 proteins; at the same time, in its evolution, sJIA can be complicated by macrophage activation syndrome (MAS)." (PMID 36361547, 2022). "In addition, free IL-18 can cause innate immune macrophage activation by inducing polarization and inflammatory and cytokine secretion and can even cause macrophage activation syndrome (MAS)." (PMID 34840991, 2021).
macrophage activation syndrome (continued). "For example, pyrin and NLRP3 are widely expressed in innate immune cells and activate pro-IL-1β, while NLRC4 is expressed in the gut and has pro-IL-18 as substrate, contributing to the development of severe enterocolitis and macrophage activation syndrome (MAS)." (PMID 34198614, 2021). "A unique property of IL-18 is the induction of FasL, which may account for the hepatic damage that takes place in macrophage activation syndrome (MAS)." (PMID 24115947, 2013). "AIFEC typically presents in infancy with systemic inflammation, macrophage activation syndrome (MAS), pancytopenia, and markedly elevated circulating IL-18." (PMID 41116055, 2025). "Emerging studies also highlight the role of IL-18 in cytokine storm diseases, particularly in conditions like macrophage activation syndrome (MAS)." (PMID 41438472, 2025). "IL-18 production is a hallmark of several monogenic immunodeficiencies that produce IBD symptoms, including macrophage activation syndrome (MAS) secondary to NLRC4 mutation, as well as mutations in X-linked inhibitor of apoptosis (XIAP)." (PMID 36986830, 2023). "Therefore, interferon-γ-related chemokines and IL–18 could predict poor prognosis related to macrophage activation syndrome in patients with SJIA." (PMID 34884842, 2021). "IL-18 is highly elevated in some HLH patients, particularly in cases of XIAP deficiency, patients with NLRC4 mutation, and macrophage activation syndrome (MAS) because of systemic juvenile idiopathic arthritis (sJIA)." (PMID 33442967, 2021). "It is important to note that circulating levels of IL-18 have been shown to be markedly elevated in patients with SJIA with macrophage activation syndrome (MAS)." (PMID 28115015, 2017). "Extremely high levels of IL-18 can be observed in patients affected by NLRC4 inflammasomopathies, or macrophage activation syndrome (MAS)." (PMID 39264518, 2024). "IL-18 also plays a role, particularly in macrophage activation syndrome (MAS)." (PMID 39624485, 2024). "Two clinical trials evaluated the effect of IL-18 inhibition using IL-18BP in adult-onset Still’s disease and NLRC4-related macrophage activation syndrome (ClinicalTrials.gov Identifier: NCT02398435, NCT03113760)." (PMID 37446301, 2023). "IL-18 has been described as part of the cytokine storm and a significative player in hemaphagocytic lymphohistiocytosis (HLH) and macrophage activation syndrome (MAS)." (PMID 36287942, 2022). "IFNg appears central to the pathogenesis of rare, hyperinflammatory states like Hemophagocytic Lymphohistiocytosis (HLH) and Macrophage Activation Syndrome (MAS), and IL-18 is both a biomarker of MAS and may be central to its pathogenesis." (PMID 36096831, 2022). "Cytokine storm, defined as macrophage activation syndrome (MAS), is characterized by the release of multiple pro-inflammatory cytokines (IL-1β, IL-18, IL-6, IL-2, IL-7, TNF-α) and chemokines (CCL2, CCL3) from macrophages." (PMID 35008658, 2021). "Driven by innate immune dysregulation and overproduction of proinflammatory cytokines (IL-1, IL-6, IL-18), AOSD presents in systemic and articular phenotypes, with severe complications like macrophage activation syndrome (MAS), fulminant hepatitis, and parenchymal lung disease." (PMID 41607599, 2025). "Extremely high total IL-18 was first observed in Adult-Onset Still’s Disease (AOSD) in 2001, and soon thereafter in Systemic Juvenile Idiopathic Arthritis (SJIA) where the highest levels were observed in patients with Macrophage Activation Syndrome (MAS)." (PMID 38183056, 2024). "Interestingly, elevated IL‐18 levels in PAPA syndrome do not correlate with an increased risk of macrophage activation syndrome (MAS), despite the assumed critical role of high IL‐18 in MAS." (PMID 38031879, 2024). "However, emerging evidence indicates that the IL-18/IL-18BP balance could be dysregulated in macrophage activation syndrome (MAS), as mirrored by the presence of free IL-18 in the circulation of patients with MAS." (PMID 37074208, 2023).
macrophage activation syndrome (continued). "In particular, the levels of CXCR9, CXCL10, CXCL11, and IL–18 were elevated in SJIA patients with macrophage activation syndrome compared with active SJIA without macrophage activation syndrome." (PMID 34884842, 2021). "Direct measurements of unbound, bioactive, free form of circulating IL-18 demonstrated that IL-18 was more specifically involved in adult-onset Still’s disease (AOSD) and systemic juvenile idiopathic arthritis (sJIA) but also in their most severe complication, macrophage activation syndrome (MAS)." (PMID 35054124, 2022).
Stroke (68 papers, 2010 to 2025). Sudden impairment of blood flow to a part of the brain due to occlusion or rupture of an artery to the brain. "Interleukin-18 (IL-18) and interleukin-12 (IL-12) are pro-inflammatory cytokines whose levels are elevated after stroke and are associated with worse clinical outcomes due to their role in enhancing Th1 responses and innate immune activation." (PMID 40869247, 2025). "Elevated IL-18 in the brain and peripheral blood has also been associated with ischemic stroke and stroke induced inflammation as well as with neurodegenerative disorders such as Alzheimer’s and frontotemporal dementia." (PMID 41013452, 2025). "NLRP3 inflammasome can activate caspase-1 state to cleaved, which in turn exposes the N-terminal of GSDMD for pore formation in cell membrane and promotes secretions of IL-1β and IL-18, causing serious of outcomes in stroke." (PMID 40289983, 2025). "IL-18 was higher in stroke patients than in controls, and was negatively associated with the NIHSS scale." (PMID 34685473, 2021). "Although interleukin-18 (IL-18) has been implicated in the pathophysiology of stroke, research findings concerning IL-18 level in stroke have been inconsistent." (PMID 31525735, 2019). "The random-effects model for the heterogeneity test showed the association between IL-18 level and the risk of stroke (case vs. control: I2 = 98.8%, p< 0.001)." (PMID 31525735, 2019). "Elevated IL-18 levels after stroke are closely associated with ischemic brain injury and increase with the aggravation of neurological impairments." (PMID 30245755, 2018). "IL-18 has not yet been found to be associated with stroke recurrence, but increased pre-stroke IL-18 levels may be related to the atherothrombotic stroke subtype." (PMID 33153204, 2020). "Furthermore, in the subgroup analysis stratified by measurement method, high IL-18 level was associated with susceptibility to stroke in the ELISA subgroup (SMD = 1.02, 95% CI = 0.46~1.58, p< 0.001) but not the Luminex xMAP subgroup (p> 0.05)." (PMID 31525735, 2019). "Thus, in the present study, we conducted a cross-sectional study in larger samples to investigate IL-18 level in acute first-episode stroke patients and to further examine the association of IL-18 level with the severity of stroke." (PMID 31525735, 2019). "Additionally, high IL-18 level was associated with susceptibility to stroke in the large-sample-size subgroup (SMD = 1.04, 95% CI = 0.40~1.68, p = 0.001) but not in the small sample size subgroup (p> 0.05)." (PMID 31525735, 2019). "The ethnicity-stratified subgroup analysis showed that increased IL-18 level was associated with stroke in the Caucasian (case vs. control: SMD = 0.72, 95% CI = 0.12~1.31, p = 0.018) and Asian subgroups (case vs. control: SMD = 1.60, 95% CI = 0.24~2.96, p = 0.021)." (PMID 31525735, 2019). "Considering other related factors that could possibly affect the association between higher IL-18 level and the pathogenesis of stroke, a stratified analysis based on countries, ethnicity, sample size and protein measurement method was conducted." (PMID 31525735, 2019). "The release of IL-18 was primarily associated with brain load (brain atrophy, DWMH, and previous stroke), while NE–MMP-9 appeared to be more closely related to acute cerebral ischemia (DMTS)." (PMID 40821836, 2025). "This aligns with research showing that inhibiting the thalamic NLRP3 inflammasome reduces IL‐18 and IL‐1β, leading to behavioral alleviation of thermal and mechanical pain sensitivity in a central post-stroke pain mouse model." (PMID 40329125, 2025). "Further large-sample clinical studies are needed to explore the relationship between IL-18 and white matter lesions at different times after stroke." (PMID 40821836, 2025). "Our study also showed that CX3CR1 gene deletion inhibited the expression of NLRP3, ASC, caspase‐1, IL‐1β, IL‐18, and NF‐κB p65 protein after stroke." (PMID 38421089, 2024).